BDNF (brain derived neurotrophic factor)
Diseases named in the same sentence as BDNF in open-access papers (continued):
Sharing a sentence is not in itself a finding about the gene and the disease.
migraine (continued). "Therefore, the alteration in BDNF metabolism may be contribute to the mechanism of migraine." (PMID 28150221, 2017). "Based on our findings that the lung microbiome can activate pulmonary vagal afferent nerves through the pulmonary BDNF‐TrkB pathway to regulate migraine, we administered 7,8‐Dihydroxyflavone (7,8 DHF), a TrkB agonist, via intratracheal injection to the migraine group." (PMID 40162625, 2025). "Migraine sufferers have been found to have significantly higher amounts of BDNF compared to the healthy population, linking this protein not just to brain plasticity but also to the regulation and central sensitization of pain." (PMID 38213956, 2024). "Such types of sensitization may be caused by the release of pro-inflammatory agents participated in the pathogenesis of migraine such as PACAP, BDNF, and CGRP." (PMID 37108677, 2023). "To understand whether estrogen had an effect on expression of BDNF, TrkB, p-ERK and p-CREB in NTG-induced migraine, we established an ovariectomized rat model prior to injection with NTG." (PMID 27875242, 2017). "Genotypic data for the BDNF gene rs6265 were available in four studies as subgroups of migraine with and without aura." (PMID 28507530, 2017). "Compared to rats that had intact ovaries, ovariectomized rats showed decreased protein expression of BDNF, TrkB, p-CREB and p-ERK in both attacks and intervals of migraines (P<0.05), while the decreased protein expression was recovered after exogenous estrogen administration." (PMID 27875242, 2017). "With RT-PCR assay, mRNA expression of BDNF, TrkB, CREB and ERK (including the ERK1 and ERK2 subunits) were found to be significantly up-regulated in the brain of both female and male rats with migraine attack compared to non-migraine control rats (P<0.05)." (PMID 27875242, 2017). "Using primary cultures of WT or KI trigeminal ganglia, we investigated whether soluble compounds that may contribute to initiating (or maintaining) migraine attacks, such as TNFα, CGRP, and BDNF, might be responsible for increasing P2X3 receptor responses." (PMID 23577145, 2013). "A subgroup analysis for migraine with and without aura did not reveal different distribution of BDNF levels." (PMID 22584531, 2012). "In this prospective bi-center study, BDNF serum levels in patients with episodic migraine with and without aura, episodic cluster headache, episodic tension-type headache, and healthy control subjects were analyzed." (PMID 22584531, 2012). "Our findings suggest that NGF, BDNF, PGE2, and VEGF may play a significant role in migraine pathogenesis and/or chronification, and therefore might bear potential value for novel targeted abortive and prophylactic migraine therapy." (PMID 34991456, 2022). "Other studies support our findings of this pro-nociceptive role of BDNF in pain chronification, where spinal BDNF mediates prolonged PGE2 sensitivity in rodents primed with IL-6 and sequestering BDNF in the cisterna magna can prevent IL-6-mediated hyperalgesic priming in a model of migraine." (PMID 29394316, 2018). "We observed that BDNF in the serum of NTG-induced migraine models was dramatically increased, both in the migraine attacks and headache-free intervals, compared to non-migraine control; and BDNF serum level was much higher in migraine attacks than in the headache-free intervals." (PMID 27875242, 2017). "Considering that estrogen has promoting effects on migraine, this study subsequently investigated the influence of estrogen on expression of BDNF, TrkB, p-CREB and p-ERK in the nitroglycerin (NTG)-induced migraine rat model to determine whether these factors mediate estrogen actions in migraine." (PMID 27875242, 2017). "However, in both groups, migraine with and without aura, BDNF was again significantly elevated during migraine attacks compared with interictal levels (P < 0.05, respectively)." (PMID 22584531, 2012).
migraine (continued). "Although mRNA expression of BDNF, TrkB, CREB, ERK1 and ERK2 were higher in the headache-free intervals of migraine than in non-migraine control, there was no statistical difference." (PMID 27875242, 2017). "Data from western blotting showed that NTG-induced migraine resulted in dramatic increase in BDNF, TrkB, p-CREB and p-ERK expression, no matter in the attack (P<0.01) and interval of migraines (P<0.05), compared to control group." (PMID 27875242, 2017). "Therefore, we propose as a possible neural mechanism by which metabolic ketosis induces an increase in BDNF release which in turn normalizes the basic interictal PREP lack of habituation and prevents migraine." (PMID 31228957, 2019).
COVID-19 (44 papers, 2020 to 2025). A disease caused by infection with severe acute respiratory syndrome coronavirus 2. "The presence of COVID-19-associated comorbidities at the time of sample collection is likely to influence circulating BDNF levels." (PMID 40709999, 2025). "SARS-CoV-2 infection dampens BDNF synthesis and release, thus favoring COVID-19 associated neurologic symptoms." (PMID 35631195, 2022). "We show a clear association between COVID-19 prognosis and circulating BDNF, as patients with lower values consistently showed worsened outcome." (PMID 34957187, 2021). "Emerging evidence links BNDF with SARS-CoV-2 infection dampens BDNF synthesis and release, which favors COVID-19 associated neurologic symptoms, however the metabolic role of BDNF in COVID-19 patients has been largely overlooked." (PMID 34957187, 2021). "Within the COVID-19 group, BDNF was higher in mothers who reported headaches or loss of smell/taste when compared with mothers without the respective symptom." (PMID 33917718, 2021). "In this small study, the authors found that recovery from COVID-19 was associated with the augment of circulating BDNF." (PMID 34957187, 2021). "We sought therefore, to examine in COVID-19 patients with different severity of the disease, the adiponectin/leptin ratio as a predictor of outcome and the association of these hormones with BDNF concentration in the circulation." (PMID 34957187, 2021). "Background and Aims: We evaluated adipose tissue-derived hormones, body composition, serum metabolic profile, levels of brain-derived neurotrophic factor (BDNF), and the association of these parameters with the clinical outcome in patients with COVID-19." (PMID 34957187, 2021). "Other data have shown that the occurrence of new or more severe headaches due to COVID-19 elicited peripheral sensitization and microglial activation associated with serum changes in BDNF, TGF-ß1, VEGF, NGF, and CX3CL1 suggestive of long-lasting severe inflammation or immune dysregulation." (PMID 39596862, 2024). "Finally, six plasma proteins were found to mediate the causal effect between LTL and COVID-19 outcomes, such as BDNF, QPCT, FAS, MPO, SFTPB, and APOF." (PMID 38882679, 2024). "It has been shown that COVID-19 may be associated with increased BDNF perhaps related to an immune response to modulate the disease." (PMID 36881624, 2023). "We have shown that it is fundamentally possible to protect and to regenerate brain tissue after intracerebral hemorrhages of various natures, in particular, those caused by COVID-19, and that the application of BDNF and uPA combination looks promising for this purpose." (PMID 35740368, 2022). "In this prospective study, we examined adipose tissue-derived hormones involved in the control of appetite and body composition, the metabolic profile, and the levels of BDNF in the circulation, and the association of these parameters with disease severity and outcome in patients with COVID-19." (PMID 34957187, 2021). "Indeed, COVID-19 critical illness was associated with low BDNF, while recovery was directly corelated with the levels of this growth factor." (PMID 34776871, 2021). "Muscle aches and deconditioning associated with severe COVID-19 presentation potentially result in the extravasation of the BDNF from skeletal muscles and, subsequently, result in epitope spreading, leaving patients at a higher risk of developing autoantibodies against the BDNF." (PMID 36832180, 2023). "In addition, performing aerobic or resistance exercises following recovery from COVID-19 may help to spur expression of BDNF, which may help to attenuate cognitive symptoms associated with LCS." (PMID 36189287, 2022). "After six months of COVID-19, patients presented lower blood levels of BDNF than subjects of the control group." (PMID 40709999, 2025). "In contrast, a decrease in BDNF levels was found in the acute phase of COVID-19, while an increase in BDNF levels was observed in patients with long COVID." (PMID 41465566, 2025).
COVID-19 (continued). "In this context, NGF and BDNF come into play as mediators known to be dysregulated in conditions of severe COVID-19, where an impairment of the central nervous system was documented." (PMID 39596862, 2024). "Probably the presence, at the time of sampling, of comorbidities associated with the COVID-19 pathology significantly influences the NGF and BDNF circulating levels." (PMID 39596862, 2024). "A subsequent study confirmed the predictive value of a decreased MMP-9/BDNF ratio for severe COVID-19 outcomes." (PMID 39596862, 2024). "A study that included 54 post-COVID-19 patients with mild neurocognitive impairment found significantly decreased serum levels of brain-derived neurotrophic factor (BDNF) compared with healthy controls." (PMID 38248798, 2024). "Another study extends previous findings, demonstrating that BDNF serum levels were decreased in COVID-19 patients and in those presenting neurological disorders associated with infection-induced hypoxia." (PMID 39596862, 2024). "Hospitalized patients with COVID-19 and those with neurological manifestations had lower serum BDNF than healthy controls while those recovering from COVID-19 infection had higher BDNF levels." (PMID 38534322, 2024). "In this sense, the relationship between NGF and BDNF and COVID-19 passes through an interventional strategy (physical exercise) aimed at restoring the physiological balance of the BDNF system." (PMID 39596862, 2024). "More recently, results in contrast with the previous ones disclosed an increase in BDNF serum levels in COVID-19 patients with neurological disorders accompanied by increased serum inflammation (TNF-α) and oxidative stress indexes (Malondialdehyde)." (PMID 39596862, 2024). "We also investigated the ratios MMP-2/-9 vs. NGF/BDNF/NFL because it was proposed as a novel method to predict COVID-19 morbidity and mortality." (PMID 36831321, 2023). "The results showed that BDNF serum levels were higher in only post-infected-COVID-19 symptomatic and future long-COVID-19 girls than healthy controls." (PMID 37408184, 2023). "BDNF levels were increased in the overall COVID-19 cohort at baseline and several subjects in the subsequent non-treatment cohort had high baseline values." (PMID 36881624, 2023). "In our cohort, we showed increased levels of IgG antibodies against BDNF in severe COVID-19 patients and in those who required supplemental oxygen." (PMID 36832180, 2023). "The results showed that COVID-19 patients had significantly lower BDNF serum levels than healthy controls." (PMID 37408184, 2023). "Undoubtedly, these studies are critical from a societal point of view, as a linear and inverse relationship between BDNF and adverse outcomes in COVID-19 patients has been reported." (PMID 37893874, 2023). "Serum level of MMP9 is found to be significantly elevated in the more severe cases of COVID-19 and in combination with brain-derived neurotrophic factor (BDNF), MMP9 has shown potential as a predictive marker for COVID-19 severity." (PMID 36768847, 2023). "In COVID-19 patients, BDNF serum levels were found to be significantly lower when in comparison with healthy controls." (PMID 37408184, 2023). "It should however be noted that the directionality and mechanisms between the relationship of BDNF and COVID-19 symptoms are complex and likely to be mediated by other signaling pathways." (PMID 36189287, 2022). "Serum BDNF levels were found to be decreased in COVID-19-positive patients and were found to be restored during recovery." (PMID 36353605, 2022). "Due to the endothelial, systemic course of the disease, VEGF A participates actively in COVID-19 development, while neurotrophic and metabolic effects of BDNF recommends for the prediction of complications in COVID-19 patients." (PMID 36438922, 2022). "Among COVID-19 patients, the described changes in the level of BDNF mainly concern its decreased level." (PMID 36294388, 2022).
COVID-19 (continued). "Oxidative stress and inflammatory biomarkers were unchanged in male and female adolescents, except for TGF-β that, similarly to BDNF, was higher in post-infected-COVID-19 symptomatic and future long-COVID-19 girls." (PMID 35626317, 2022). "Considering the interrelation of MMP-9 and BDNF, to our knowledge, for the first time, we analysed MMP-9/BDNF ratio in the COVID-19, in order to link these mediators with stages of disease development." (PMID 36438922, 2022). "Changes in the levels of serum BDNF were observed in post-infected-COVID-19 symptomatic patients, predicting an intensive care admission and a worse prognosis." (PMID 35911513, 2022). "NGF and BDNF values in acute and remission phases of COVID-19 patients were first compared with those assessed in the six controls." (PMID 36579579, 2022). "Overall, the findings described herein highlight the importance of NGF and BDNF as dynamic biomarkers for monitoring disease and reinforces the possibility of using saliva and sera for quick, non-invasive COVID-19 screening." (PMID 36579579, 2022). "This study aims to evaluate the levels of circulating and salivary NGF and BDNF in COVID-19 patients, comparing their expression between acute and remission phases of disease." (PMID 36579579, 2022). "For this reason, BDNF levels have been proposed as a predictive factor of intensive care unit admission in COVID-19 patients." (PMID 35631195, 2022). "Presented data describe for the first time the high-level systemic MMP-9/BDNF ratio in patients with COVID-19." (PMID 36438922, 2022). "High levels of cortisol and inflammatory cytokines in both MS and COVID-19 downregulate the protective effects of BDNF against neuronal cell apoptosis." (PMID 35492581, 2022). "Recently, Azoulay and co-workers observed a correlation between the increase in circulating BDNF and the improvement in COVID-19 symptoms." (PMID 36579579, 2022). "In a study involving 64 COVID-19 (+) patients there was a significant reduction in BDNF level among patients as compared to the control group." (PMID 36294388, 2022). "In a case report, Petrella and coworkers introduced the possibility to use serum NGF and BDNF as new predictive biomarkers of COVID-19’s long-term effects, especially in girls." (PMID 36579579, 2022). "(2020) showed that COVID-19 patients with moderate to severe disease showed decreased circulating content of BDNF when compared with those presenting milder symptoms (–~15%)." (PMID 34957187, 2021). "In summary, according to this prospective study, BDNF and BDNF/adiponectin ratio are possible markers of adverse clinical outcomes for COVID-19." (PMID 34957187, 2021). "In contrast to COVID-19 and unexposed groups, BDNF concentration in human milk was lower in mothers with mastitis than in mothers without mastitis." (PMID 33917718, 2021). "Unfortunately, so far only one study mentions the relationship between BDNF and COVID-19, but its results are promising and it is worth doing more research in this direction." (PMID 34575258, 2021). "We report a linear and inverse relationship between BDNF and adverse outcomes in patients with COVID-19." (PMID 34957187, 2021). "The ratio of BDNF/ adiponectin varies in parallel with different severities and outcomes, pointing out that adipose endocrine function is important in COVID-19." (PMID 34957187, 2021). "Our study reveals that NGF concentrations in human milk were lower in mothers with a COVID-19 PCR test and mothers with viral symptoms suggesting COVID-19 than in unexposed mothers, but BDNF was comparable." (PMID 33917718, 2021). "We demonstrated that NGF concentrations in human milk were lower in the COVID-19 PCR and viral symptoms groups than in the unexposed group, but BDNF was comparable." (PMID 33917718, 2021). "As lymphocytes contribute to the secretion of BDNF, lymphopenia induced a reduction of BDNF secretion in patients with severe COVID-19." (PMID 33917718, 2021).